MIR4483 (microRNA 4483)
Synonyms: hsa-mir-4483
Gene: MicroRNA gene on chromosome 10 (113,777,993 to 113,778,054, reverse strand). Ensembl gene ENSG00000283656.
Diseases named in the same sentence as MIR4483 in open-access papers:
MIR4483 is named in the same sentence as 2 diseases in open-access papers, as found by Europe PMC text mining. Sharing a sentence is not in itself a finding about the gene and the disease. The quoted sentences say what the papers report.
migraines (1 paper, 2016). "The upstream region of the HABP2 gene is associated with migraines without aura, and the intergenic region between the PLEKHS1 and MIR4483 genes is associated with obesity − related traits." (PMID 27230431, 2016).
MIR4483 also shares sentences with these, for which no sentence is quoted: Obesity (1 paper).